DNMT3A (DNA methyltransferase 3 alpha)
Diseases named in the same sentence as DNMT3A in open-access papers (continued):
Sharing a sentence is not in itself a finding about the gene and the disease.
myeloid neoplasm (continued). "While TET2 and DNMT3A mutations are two of most common genetic variations in CHIP and can precede myeloid malignancies, recent studies have also revealed associations between CHIP and other comorbid diseases." (PMID 31963585, 2020). "Our dataset contained neutral polymorphisms and mutations associated with myeloid malignancies from epigenetic regulators ASXL1, DNMT3A, EZH2, and TET2." (PMID 24348198, 2013). "We examined the entire coding sequences of DNMT3A gene by high-resolution melting analysis and sequencing in Chinese patients with myeloid malignancies." (PMID 22066015, 2011). "For example, Park and Yoshizato showed that the most common mutations in AA patients were BCORL1/BCOR, ASXL1, DNMT3A and TET2, among which AA patients with myeloid tumor-related mutations, such as ASXL1, DNMT3A, RUNX1, showed approximately 40-60% response and overall survival after IST." (PMID 39873798, 2025). "Clonal hematopoiesis of indeterminate potential (CHIP) serves as a critical precursor to leukemogenesis, characterized by recurrent mutations—most frequently in DNMT3A, TET2, and ASXL1—that emerge in otherwise healthy individuals and significantly elevate the risk of AML and other myeloid neoplasms." (PMID 41451201, 2025). "While the PI3K pathway has been targeted for treatment in some lymphoid malignancies, its role in DNMT3a loss-of-function–associated development of myeloid malignancies has not been investigated." (PMID 36976647, 2023). "Bulk sequencing studies on the peripheral blood (PB) of normal individuals with no overt signs of myeloid malignancies have revealed that DNMT3A mutations occur as preleukemic somatic mutations that can be later detected in patients with full-blown AML." (PMID 36976647, 2023). "Interestingly, while DNMT3A R882 mutations were found to be enriched in AML (~50% of all DNMT3A mutations), they are decreased in frequency in CHIP (~10%) and other myeloid neoplasms including MDS (~25–30%)." (PMID 36831294, 2023). "As TET2/DNMT3A‐mutated progenitor cells can differentiate into multilineage progenies and give rise to both AITL and myeloid neoplasms, they may also have the potential to lead to other metachronous/synchronous neoplasms." (PMID 35064935, 2022). "Given that MDS is a myeloid neoplasm with the potential of AML transformation, it suggests that R882 mutations could also confer a higher risk of AML transformation than other DNMT3A mutations in MDS." (PMID 35296003, 2022). "While methylation therapies targeting DNMT3A-mutated myeloid neoplasms exist, such targeted therapies are not currently in use for T-cell lymphomas with DNMT3A mutations." (PMID 33801781, 2021). "Understanding the impact of inactivating TET2 and DNMT3A mutations on myeloid cells is critical for elucidating the connection between CHIP, inflammation, and the pathogenesis of comorbid disease, as well as myeloid malignancies." (PMID 31963585, 2020). "Similarly, Dnmt3a ablation in HSCs predisposes mice to develop a spectrum of myeloid and lymphoid malignancies, and Dnmt3a-KO-derived myeloid malignancies and T cell acute lymphocytic leukemia/lymphoma show distinct methylation aberrations." (PMID 27229519, 2016).
myeloid neoplasm (continued). "The mechanisms of leukemogenesis by DNMT3A are not entirely clear; however, studies have shown that heterozygous Dnmt3a ablation in mice leads to an expansion of the HSC pool, myeloid skewing and a predisposition to myeloid malignancies that may require additional genetic alterations." (PMID 29527516, 2018). "The interplay between DNMT3A and TET2 in myeloid neoplasms underscores a delicate balance in epigenetic regulation required for normal hematopoiesis." (PMID 40374809, 2025). "In myeloid malignancies, multiple alterations were noted in TET2 (n = 142, including 24/43 or 56% of AITL samples) and DNMT3A (n = 35), while in mantle cell lymphoma, ATM (n = 14, 10%) frequently harbored multiple mutations." (PMID 37898613, 2023). "Around 60% of CD34+ cells from patient 2 [P2(h)] exhibited a heterozygous JAK2V617F mutation (JAK2V617F/WT) whereas no mutation was identified in these cells in ASXL1 and the other genes involved in myeloid malignancies, including TET2, EZH2, DNMT3A, IDH1 and SRSF2." (PMID 24066127, 2013). "Interestingly, genes commonly mutated in AML and other myeloid neoplasms, such as FLT3, NPM1, KIT, RUNX1, and DNMT3A, were absent in our cohort." (PMID 40526100, 2025). "For example, microhomology-mediated recurrent deletions of CALR, ASXL1, and SRSF2 and non-recurrent deletions in TET2, DNMT3a, CEBPA, and RUNX1 have been reported in myeloid neoplasms." (PMID 36011278, 2022).
hepatocellular carcinoma (40 papers, 2014 to 2026). A malignant tumor that arises from hepatocytes. "In addition, overexpression of DNMT1, 3A, and 3B was correlated with tumorigenesis and other diseases, and DNMT3A expression was significantly associated with the prognosis of gastric and hepatocellular carcinomas in human." (PMID 29312436, 2017). "In addition, miR-101 has been shown to cause aberrant DNA methylation in hepatocellular carcinoma tissue by targeting DNMT3a." (PMID 25309892, 2014). "For example, miR-30a-3p inhibits hepatocellular carcinoma cell proliferation via the PI3K/AKT signaling pathway by targeting DNMT3a and suppresses renal cell carcinoma invasion and metastasis by targeting ATG12." (PMID 41361055, 2025). "Many studies have shown that dysregulation of DNMT3A leads to oncogenesis in several cancer types, including gastric cancer, hepatocellular cancer, and colorectal cancer." (PMID 39284825, 2024). "It is interestingly identified that DNMT3a upregulation partially reduces PTEN level in hepatocellular carcinoma cells, showing the inverse relation between DNMT3a and PTEN." (PMID 34623601, 2022). "Survival analyses with the univariate Cox regression model revealed their crucial roles in the patient outcomes, of these, DNMT3A, UHRF1, DNMT1, DNMT3B and TET1 the risk factors for hepatocellular carcinoma." (PMID 35771147, 2022). "In human hepatocellular carcinoma tissues and cell lines, miR-30b-5p expression is significantly downregulated, and this miRNA mediates DNMT3A to repress proliferation." (PMID 34336638, 2021). "circSOD2 expression enhanced cancer cell growth, cell migration, cell cycle progression, and in vivo tumor growth in hepatocellular cancer; circSOD2 inhibited miR-502-5p expression, thereby upregulating DNMT3A expression." (PMID 33946584, 2021). "Moreover, either DNMT3A or DNMT3B is found in many clinical tumor samples, and the increased expression of DNMT3A was previously reported to participate in the progression of hepatocellular carcinoma." (PMID 31311130, 2019). "In HBV-associated hepatocellular carcinoma (HCC), DNMT expression is inversely correlated with levels of tumor suppressor microRNAs (miRNAs), including miR-152 targeting DNMT1 and miR-101 targeting DNMT3A." (PMID 29438328, 2018). "Moreover, has-miR-450a was reported to be significantly decreased in hepatocellular carcinoma as well as ectopically; its expression leads to cell proliferation inhibition through DNMT3a." (PMID 27418141, 2016). "Similarly, DNMT3A-mediated promoter methylation causes PTEN gene silencing and promotes hepatocellular carcinoma cell proliferation." (PMID 26350239, 2015). "Similarly, in hepatocellular carcinomas, there is increased expression of DNMT1, DNMT3a, and DNMT3b and a progressive increase in the number of methylated genes from normal liver, chronic hepatitis/cirrhosis to hepatocellular carcinoma." (PMID 24822169, 2014). "The depletion of DNMT3A was observed to result in demethylation of the PTEN promoter in hepatocellular carcinoma (HCC) cells, thereby indicating that DNMT3A silences PTEN through DNA methylation." (PMID 40531759, 2025). "However, DNMT3A depletion in hepatocellular carcinoma cells resulted in reduced proliferation." (PMID 32576961, 2020). "Furthermore, miR-21 can regulate the expression of DNMT3A, and thereby control the activation of the promoter regions that promote hepatocellular carcinoma (HCC) cell growth and proliferation." (PMID 38033863, 2023). "In this article, we aimed to explore the potential protective effect of curcumin against UV radiation-induced DNMT1, DNMT3A, DNMT3B, HDAC5, and HDAC6 expression in immortalized keratinocytes (HaCaT), hepatocellular carcinoma (HepG2), and lung adenocarcinoma (A549) cells." (PMID 41901340, 2026).
hepatocellular carcinoma (continued). "Likewise, elevated expressions of DNMT3A and DNMT3B have been observed in many patient samples, with heightened levels of DNMT3A contributing to the development of hepatocellular carcinoma." (PMID 39996888, 2025). "Taken together, these results prove that HBx downregulates PTPN13 expression via epigenetic silencing and that DNMT3A physically binds to the PTPN13 promoter at a site −343 to −313 bp upstream of the transcription start site, leading to DNA methylation in hepatoma cells." (PMID 33051595, 2021). "Similarly, the recruitment of DNMT1 and DNMT3a to the promoters of the secreted frizzled-related protein SFRP1 and SFRP5 is facilitated by HBx, leading to their downregulation in hepatoma cells and HCC patients." (PMID 33923385, 2021). "Similarly, DNMT3A-mediated methylation reduces PTEN expression and promotes hepatocellular carcinoma cell proliferation and colony formation." (PMID 29717263, 2018). "Similarly, depletion of DNMT3A restored the expression of various TSGs (including PTEN) that participate in cell cycle regulation, transcription regulation, and signal transduction in hepatocellular carcinoma (HCC)." (PMID 28423585, 2017).
gastric cancer (39 papers, 2009 to 2025). A primary or metastatic malignant neoplasm involving the stomach. "In the case of DNMT3A rs1569686, multiple gene models were connected to a decreased risk of gastric cancer." (PMID 37878642, 2023). "Taken together, these results suggest that EBV infection is highly associated with DNMT3A expression in gastric cancer cells, indicating epigenetic modification." (PMID 34503060, 2021). "Despite the involvement of rs1550117, a known representative polymorphism of DNMT3A reported in various carcinomas, its role in gastric cancer is still controversial, particularly in Japanese patients." (PMID 33066747, 2020). "Recently, we found that rs6733868 C > G and rs13428812 A > G of DNMT3A are involved in HP infection, the progression of gastric mucosal atrophy, and gastric cancer susceptibility in a Japanese population." (PMID 33066747, 2020). "Although the DNMT3A polymorphism has been reported to be associated with gastric cancer, HP infection, and gastric mucosal atrophy, its association with methylation of gastric mucosa genes has not been clear." (PMID 33066747, 2020). "The de-regulation of the miR-29 family and DNA methyltransferase 3A (DNMT3A) is associated with gastric cancer (GC)." (PMID 25874772, 2015). "Our previous study found a functional SNP rs1550117 in DNMT3A promoter that can increase its transcriptional activity and contribute to the genetic susceptibility to gastric cancer in a Chinese population." (PMID 24667323, 2014). "It has recently been found that the DNMT3A polymorphism rs1550117 alters the promoter activity and risk of gastric cancer and CRC." (PMID 23666104, 2013). "In this hospital-based case-control study, we genotyped a functional DNMT3A polymorphism and investigated the association between this genetic variant and the risk of gastric cancer and oesophagus carcinoma." (PMID 20128888, 2010). "In addition, it is possible that the chemotherapy regimen is associated with specific changes in the DNMT3A gene, as shown in a variety of genes in gastric cancer chemotherapy studies." (PMID 37372315, 2023). "Meta-analysis of the association of DNMT3A(rs1550117) polymorphism with risk of gastric cancer." (PMID 37878642, 2023). "To test this hypothesis, we investigated how EBV infection is associated with the expression of the DNMT3A gene in gastric cancer cells." (PMID 34503060, 2021). "We previously demonstrated that DNMT3A polymorphisms (rs6733868 and rs13428812) are associated with the severity of gastric mucosal atrophy, which is accompanied by chronic inflammation and the subsequent development of gastric cancer." (PMID 33066747, 2020). "The aim of this study was to investigate the role of a DNMT3A promoter genetic variant on its transcriptional activity and to evaluate the association between DNMT3A gene polymorphism and the susceptibility to gastric cancer (GC) and oesophagus carcinoma (EC) in the Chinese population." (PMID 20128888, 2010). "Overexpression of DNMT3A was found in oral squamous cell carcinoma and hepatocarcinogenesis, and increased expression of all three DNMTs was found in gastric cancer compared to normal tissue." (PMID 40507223, 2025). "There is evidence that hsa‐miR‐29c‐5p is an important regulator of CDC42 and DNMT3A genes in the pathogenesis of gastric cancer." (PMID 35585716, 2022). "A meta-analysis in gastric cancer suggested that rs16999593 in DNMT1 and rs1550117 in DNMT3A could contribute to GC risk and that rs1569686 in DNMT3B might be a protective factor." (PMID 35965507, 2022). "Meanwhile, high DNMT3A mRNA levels implied poorer overall survival from gastric carcinoma (p = 0.0095, hazard ratio = 1.64)." (PMID 34503060, 2021). "Kaplan–Meier analysis showed that a low DNMT3A mRNA level was significantly correlated with better overall survival from gastric carcinoma." (PMID 34503060, 2021).
gastric cancer (continued). "As for the competing pairs, miR-29b/c was shown to suppress the downstream gene DNMT3A, and in turn, miR-29b/c was suppressed by DNMT3A in a DNA methylation-dependent manner in gastric cancer." (PMID 32127798, 2020). "The positive correlations between DNMT3A/DNMT3B with PTGS2 was validated in an independent gastric cancer cohort (GSE27342)." (PMID 31534549, 2019). "Up-regulation of DNMT3A was already correlated with the down-regulation of hsa-miR-29c-5p in cutaneous melanoma and in gastric cancer." (PMID 30376837, 2018). "A previous study, in a gastric cancer cell line, showed that quercetin and isoliquiritigenin decreased DNMT1 and DNMT3a protein levels, causing slight demethylation of the promoter region of the BCL7A gene." (PMID 30409182, 2018). "Here, we show that DNMT3A isoform b (DNMT3Ab), a member of the DNMT3A isoform family, is critical for directing epithelial–mesenchymal transition (EMT)-associated metastasis in gastric cancer (GC)." (PMID 29717263, 2018). "Here, we reported that the exogenous expression of DNMT3A promoted gastric cancer (GC) cell proliferation by accelerating the G1/S transition." (PMID 26350239, 2015). "A similar study revealed the RNF180/DNMT3A/ADAMTS9 axis in gastric cancer." (PMID 39048965, 2024). "Additionally, we found a significantly higher expression of DNMT3a in the chemotherapy‐resistant (Non‐response) group compared to the chemotherapy‐sensitive group (Response) in the GSE62254 cohort of gastric cancer patients." (PMID 37477089, 2023). "DNMT3a is overexpressed in gastric cancer tissues, where it localizes to the cell cytoplasm." (PMID 35054489, 2022). "Similarly, it has been indicated that 5-Aza-CdR inhibits the activity of DNMT3a and DNMT3b in gastric cancer cell lines SGC7901 and BGC823 thereby up-regulate tumor suppressor gene RASSF1A." (PMID 34319031, 2021). "DNMT3A expression in gastric cancer (GC) has only been studied in protein levels and showed a significant overexpression of DNMT3A in tumours while DNMT1 and DNMT3B were only modestly over-expressed." (PMID 20128888, 2010). "Aberrant promoter methylation in various tumour suppressor genes is also involved in human gastric cancer and oesophagus carcinoma and the epigenetic silencing linked this aberrant de novo methylation of CpG islands to the overexpression of the DNMT-3 family (DNMT3A and DNMT3B)." (PMID 20128888, 2010). "Recent evidence has also implicated RNautophagy in the development of chemoresistance to decitabine in gastric cancer, where SQSTM1-mediated degradation of Linc00942 leads to elevated DNA methylation levels via increased DNMT3A expression." (PMID 39164641, 2024). "RNF180 ubiquitinates DNMT3A, markedly reducing ADAMTS9 methylation levels and increasing its expression in gastric cancer." (PMID 39048965, 2024). "Accordingly, clinical data from TCGA database suggested that higher DNMT3a expression was correlated to shorter overall survival and post progression survival in gastric cancer patients, strongly indicating that upregulated DNMT3a may mediate chemoresistance in gastric cancer." (PMID 37477089, 2023). "Taken together, these findings suggest that both DNMT3A downregulation and ATM upregulation are likely to produce better overall survival outcomes for gastric cancer patients." (PMID 34503060, 2021). "Thereafter, we investigated how the mRNA levels of DNMT3A and ATM were correlated with the overall survival of gastric cancer patients." (PMID 34503060, 2021). "Up-regulation of CDC42 and DNMT3A genes and down-regulation of APC gene in gastric cancer have several implications in the malignancy of the cell." (PMID 30376837, 2018). "The same authors also found that overexpression of DNMT3A is responsible for methylating the CpG islands in the CDH1 promoter region, which lead to E-cadherin down regulation and increased malignancy of gastric cancer cells." (PMID 30376837, 2018).